CCR10 (C-C motif chemokine receptor 10)
Diseases named in the same sentence as CCR10 in open-access papers (continued):
Sharing a sentence is not in itself a finding about the gene and the disease.
cancer (40 papers, 2013 to 2025). A tumor composed of atypical neoplastic, often pleomorphic cells that invade other tissues. "Activated CCL28 binds to CCR3 and CCR10, and can control the targeted migration of TILs, Tregs, and cancer‐associated stellate cells." (PMID 36952458, 2023). "In particular, it participates in the recruitment of Treg, and in pancreatic ductal adenocarcinoma, in the recruitment of cancer-associated stellate cells caused by the expression of CCR10 on these cells." (PMID 33076281, 2020). "Chemokines such as CCR7, CCR9, and CCR10, have been identified as having the potential to support the metastatic seeding of cancer cells." (PMID 40852716, 2025). "Although CCR10 and its ligands are well established in disease pathogenesis, emerging evidence highlights their potential in cancer immunotherapy." (PMID 41050670, 2025). "The G-protein-coupled receptor, cc chemokine receptor 10 (CCR10), plays a vital role in the occurrence and development of various malignant tumors." (PMID 38429844, 2024). "With regards to chemokines and chemokines receptors, our results revealed significantly positive correlations of HIC1 with CXCL12 and CCR10 in several cancers." (PMID 37388742, 2023). "Due to the production of CCL28 and CCL27 in the skin, the expression of CCR10 on a cancer cell increases the probability of skin metastasis." (PMID 33076281, 2020). "CCR10 has also been involved in cancer growth and invasion in adult T-cell leukaemia/lymphoma and chronic lymphocytic leukaemia." (PMID 30591657, 2018). "High expression of CCR4 and CCR10 correlated with poor cancer‐specific survival (p < 0.045)." (PMID 40896244, 2025). "Our survival analysis revealed that high expression of CCR3, CCR4, and CCR10 is associated with poor cancer‐specific survival in FL‐patients, a finding that has not been reported previously." (PMID 40896244, 2025). "Deepening our understanding of CCR10 could thus unlock novel, precision-tailored interventions for immune modulation and cancer treatment." (PMID 41050670, 2025). "Accumulating evidence suggests that CCR10 is involved in cancer progression." (PMID 38429844, 2024). "Additionally, the mRNA levels of Treg chemokine receptors Ccr4, Ccr8, and Ccr10 as well as their ligands, Ccl1, Ccl17, and Ccl22 are significantly upregulated in the v-rasHa/ΔNp63α carcinomas compared to v-rasHa/Stuffer tumors or normal skin." (PMID 37638000, 2023). "Similarly, the interaction between CCL28/CCR10 is described as responsible for the remodeling of lymphatic vessels, increasing the metastatic potential of cancer cells." (PMID 33066172, 2020). "CCR7, CCR9, and CCR10 were also described to directly support metastatic seeding of cancer cells." (PMID 30591657, 2018). "To determine whether other drugs or metabolites used to treat or have potential for treating MS or cancer patients might affect the expression of CCR10 on NK cells similar to GA, we investigated the effects of various drugs." (PMID 27807435, 2016). "However, the molecular and biochemical signaling pathways by which CSC-DC vaccination induces down-regulation of CCR10 on cancer cells, particularly on cancer stem cells, and down-regulation of CCL27 and CCL28 in metastatic target organs have yet to be identified." (PMID 29423335, 2017). "The heatmap displayed that GPX4 expression was highly correlated with the levels of numerous chemokines and chemokine receptors, such as CXCL16, CCL28, CX3CL1, CCL5, CCR10, CXCR5, and CXCR3, across the majority of cancer types." (PMID 41142608, 2025). "Receptor genes in LIHC, LUSC, PRAD, STAD, and THYM exhibited significant subcluster differences, with CCR10, CCR5, and CXCR6 differing in more than 15 cancer types." (PMID 41150760, 2025).
cancer (continued). "In addition, SERPINH1 also related to their receptors in pan-cancer, such as CXCR4, CCR1, and CCR10." (PMID 36105106, 2022). "In addition, we can find that its expression positively related to multiple chemokines receptors in pan-cancer, such as CXCR4, CCR1, and CCR10." (PMID 36105106, 2022). "An intestinal immune network for IgA production might provide new markers in enteric DLBCL, such as CCR10, TNFRSF13B, AICDA, and HLA-DOB, as well as genes involved in transcriptional misregulation in cancer (NFKBIZ, FUT8, LMO2, CCND2, BCL2A1, ETV6, and CDK14)." (PMID 29992138, 2018).
infection (11 papers, 2011 to 2024). The state of being infected such as from the introduction of a foreign agent such as serum, vaccine, antigenic substance or organism. "Our results indicate that CCL28 contributes to neutrophil accumulation and activation, with its receptors CCR3 and CCR10 upregulated in the mucosa during infection, where up to ~50% of neutrophils express surface CCR3." (PMID 39193987, 2024). "Intracellular stores of CCR10 were also detected in some bone marrow neutrophils under homeostatic conditions, with a small but significant increase during STm infection." (PMID 39193987, 2024). "We find that during infection with the original Wuhan strain, plasmablasts in blood produce IgA1, IgG1, and IgM, and that most express CCR10 and integrin β1, only some integrin β7, while the majority lack CCR9." (PMID 37071584, 2023). "However, CCR10 was expressed on the surface of only ~0.3% uninfected bone marrow neutrophils, increasing to ~0.6% during STm infection." (PMID 39193987, 2024). "There was a higher level of CCR10 on CD3+ T cells after infection by PEDV." (PMID 35758666, 2022). "The gene ccr10 (chemokin receptor 10) is located about 100 kb downstream the first significant SNP, which has known chemotactic activity, and changes in expression of genes from the same family have been reported as part of the acute response of infection of S. iniae in Nile tilapia." (PMID 36936431, 2023). "Both receptors were present on a small subset of bone marrow neutrophils (~4% CCR3, ~0.2% CCR10) and blood neutrophils (~5% CCR3, ~1% CCR10) during infection." (PMID 39193987, 2024). "In contrast, the expression levels of CD186, CXCR5, CCR9, CCR10 and CD103 were unaffected by the infection." (PMID 36298634, 2022). "In naive cells, the expression levels of CCR10, CXCR3, and CCR6 were similar during infection." (PMID 39867906, 2024). "Interestingly, expression of skin-homing receptors CCR4 and CCR10 was up-regulated in CD4+ cells from the mesLNs and in the circulation of worm-infected mice 2 and 3 weeks after infection." (PMID 34931000, 2022). "In contrast to the reported properties of peripheral blood derived Th22 cells without a characterised antigen specificity, IL-22 production in response to PA infection was from memory CD4+ T cells that did not express the skin-homing receptors CCR4 or CCR10." (PMID 24587305, 2014). "In our studies, CCR5, CCR10 and CXCR6 were slightly up-regulated at the early infection." (PMID 21819625, 2011). "Since the main function of these cells is the maintenance of homeostasis, a higher migration of CCR10+ B cells into milk may not be as relevant during infection." (PMID 39867906, 2024).
inflammation (1 paper, 2015). Aberrant reaction of the microcirculation characterized by movement of fluid and leukocytes from the blood into extravascular tissues. "A role for CCL28 and CCR10 in various models of lung inflammation in mice has also been suggested." (PMID 26112287, 2015).
CCR10 also shares sentences with these, for which no sentence is quoted: allergic contact dermatitis (4 papers); multiple myeloma (3); idiopathic pulmonary fibrosis (2); mycosis fungoides (2); ovarian tumor (2); squamous cell carcinoma (2); adenocarcinoma (1); Alzheimer disease (1); autoimmune disorder (1); Cirrhosis (1); cutaneous squamous cell carcinoma (1); dengue (1); dental caries (1); gastric cancer (1); gastric tumor (1); inflammatory bowel disease (1); intestinal infection (1); leukemia (1); lung squamous cell carcinoma (1); mastitis (1); nervous system cancer (1); oral cancer (1); oral squamous cell carcinoma (1); osteoarthritis (1); primary biliary cholangitis (1); prostate carcinoma (1); psoriatic arthritis (1); rectal cancer (1); skin inflammatory disorders (1); systemic sclerosis (1).
A further 1 disease shares a sentence with CCR10 in 1 paper.